LEP (leptin)
Diseases named in the same sentence as LEP in open-access papers (continued):
Sharing a sentence is not in itself a finding about the gene and the disease.
tumor (continued). "This can be reinforced by the evidence that circulating levels of leptin, the predominant hormone secreted by adipocytes, were significantly higher in tumor patients compared to normal subjects." (PMID 37509120, 2023). "Leptin can also influence the frequency of mitochondrial respiration in CD8+ T cells derived from peripheral lymph nodes near the tumor site, thus enhancing CD8+ T cells' tumor-killing function in a melanoma model." (PMID 37554282, 2023). "Leptin and adiponectin levels, as well as the leptin–adiponectin ratio, were assessed by the tumor grade." (PMID 37444627, 2023). "Studies have reported the role of leptin in cell proliferation, suppression of apoptosis, and tumor cell development." (PMID 38068717, 2023). "We identified two mechanisms through which the fasting-induced reduction in insulin, IGF1 and leptin cooperates with CBIs to lower intratumour cholesterol and to slow tumour growth." (PMID 37907500, 2023). "Leptin, adiponectin, and visfatin indirectly participate in the tumor formation process through key molecules such as AMPK, STAT, and PI3K." (PMID 36811728, 2023). "In particular, in prostate cancer, the adipokines leptin, visfatin, and resistin have been related as promoters of various stages of tumor progression." (PMID 38137922, 2023). "The higher levels of leptin and/or ObRs in patients with tumor invasion and distant metastasis and their correlation with decreased relapse-free survival support the consideration of leptin as a poor prognostic factor." (PMID 37686525, 2023). "Adipose tissue produces a number of adipokines displaying modulatory effects on surrounding cells, the most extensively studied of which is leptin, which stimulates tumor growth, metastasis, inflammation, and angiogenesis." (PMID 37895840, 2023). "The result also showed that the plasma level of leptin also positively correlated with the size indexes, both tumor volume (r = 0.21, and p = 0.048) and maximum diameter of tumor (r = 0.16, and p = 0.045)." (PMID 37509115, 2023). "Adipose factors, such as leptin, can enhance inflammation, stimulate or block other immune molecules, and maintain the environment for tumor growth and development." (PMID 37940857, 2023). "(F) Xenograft tumor growth in nude mice from E11-KO H1299 cells transfected with scrambled siRNA or a siRNA against Leptin or p73γ (error bars represent SEM, * indicates p<0.05 by Student’s t-test)." (PMID 37650871, 2023). "In contrast, other reports indicate that leptin can regulate tumor proliferation and invasion via signaling pathways." (PMID 37190027, 2023). "Leptin promotes the growth and proliferation of tumour cells by activating various signalling pathways." (PMID 37592827, 2023). "The downstream effects of leptin signaling, through the activation of specific signaling pathways in tumor cells, such as the JAK/STAT3 and PI3K/AKT pathways, can promote carcinogenesis." (PMID 37509120, 2023). "Concurrently in PCa, leptin was shown to increase cell proliferation and suppression of apoptosis, thereby enhancing tumor growth." (PMID 38068717, 2023). "A recent study reported that inhibition of ATX-LPA-Lpar2-p38-leptin axis in the mouse HCC model can inhibit tumor growth." (PMID 37266440, 2023). "A comprehensive revision that compiled the miRNAs controlled by three of the main adipokines (i.e., adiponectin, leptin, and resistin) that influence certain tumor diseases has been published." (PMID 37819510, 2023). "For example, metformin can exert anti-tumor effects by regulating adipocyte leptin and reversing dysfunctional adipocytes and normalizing them." (PMID 37666813, 2023). "Consistent with this, the tumor size and weight were much less for E11-KO tumors injected with p73γ or Leptin siRNA than the ones injected with the control scrambled siRNA." (PMID 37650871, 2023). "There was much lower VHL level but endowed with higher HIF1A, LEPTIN, UCP1 and phosphorylated HSL protein expression in tumour associated adipose tissue as well." (PMID 37620316, 2023).
tumor (continued). "Noteworthy, Raut and coworkers demonstrated that leptin, one of the major adipokines produced in obese conditions and related to tumor growth, is able to activate NLRP3 inflammasomes in MCF-7 breast cancer cells." (PMID 37819510, 2023). "Leptin has been shown to be responsible for reducing the anti-tumor effects of chemotherapy via activation of AKT and STAT3 pathways, as well as upregulating Bcl-2 expression and inhibiting caspase-3 activation in MM cells in vitro." (PMID 36909335, 2023). "In our study, leptin level was higher while IL-4 level was lower in the tumor animals compared to other animals." (PMID 36834959, 2023). "Consistently, the protein abundance of LEPTIN was highly induced in eWAT and iWAT from mice receiving 10A/miR-204 sEVs or tumour-bearing mice compared to their respective control groups." (PMID 37620316, 2023). "TGF-β is an inflammatory cytokine that bridges leptin and inflammatory response since it modulates the release of leptin from adipose and tumor cells." (PMID 37155466, 2023). "Multiple studies have shown that Leptin is related to tumor development and fatigue symptoms and can affect tumor progression and fatigue occurrence through the regulation of metabolism, immune, and neuroendocrine systems, among others." (PMID 37542585, 2023). "A synthetic FXR agonist, GW4064, inhibits the leptin-induced tumor-promoting activities of CAFs and CAF-conditioned medium in BC cells by inhibiting growth, motility, and invasiveness in vitro." (PMID 37046676, 2023). "First, adipocytes can support the survival and growth of tumor cells by secreting various cytokines, adipokines, and growth factors, such as IL-6 and leptin." (PMID 37345073, 2023). "Signalling pathways mediated by leptin play an important role in tumour cell proliferation, invasion and metastasis." (PMID 37238197, 2023). "Among them, leptin, resistin, visfatin and apelin are abundant in the plasma of obese individuals, correlate positively with the amount of fat, and have tumor-promoting functions." (PMID 36291097, 2022). "Together, our data indicated that miR-628 is downregulated in PCa tumor samples compared to normal matched controls, and the expression of miR-628 is controlled by adipokine leptin in PCa cells." (PMID 35710817, 2022). "When compared to pre-tumour endpoint, leptin levels were further increased at tumour endpoint for HFD mice, likely reflecting the weight gain of HFD mice at this later timepoint." (PMID 35908046, 2022). "The impact of gain- or loss-of-function of leptin were determined by MTT, colony formation, wound healing, and Transwell assays in NPC cells, and by a xenograft tumor model." (PMID 35778755, 2022). "Leptin-induced metabolic support allows immune cells to be polyfunctional, proliferative, and mediate tumor control; decreased TRegs; increased KLRG1hiCD127+ memory precursors." (PMID 35640930, 2022). "At tumour endpoint, serum levels of adiponectin and leptin were assessed by ELISA and compared to pre-tumour endpoint." (PMID 35908046, 2022). "We first used an osmotic pump to deliver fluorescently labelled leptin to the circulation and verified leptin’s ability to enter both normal skin dermis and tumour stroma from circulation." (PMID 36450983, 2022). "Consistent with a pro-inflammatory role for leptin, treatment of lean mice with leptin was sufficient to increase anti-tumor immunity to an extent similar to PD-1 blockade." (PMID 35039633, 2022). "CCL8 and Leptin were specifically secreted in the juxta-tumor supernatants at heterogeneous concentrations." (PMID 36539890, 2022). "Addition of leptin rescued defective tumor growth in GLSECKO hosts, compared with those treated with vehicle controls." (PMID 36381236, 2022). "The soluble factors derived from adipocytes, called adipokines, including adiponectin, leptin, IL-6, and tumor necrosis factor α, are involved in tumor progression." (PMID 35805003, 2022).
tumor (continued). "Increase adiposity, and thus increased leptin secretion, promotes tumor cell proliferation as an independent factor for neoplastic aggressiveness, with functions strengthened through interactions with multiple oncogenes, growth factors, and cytokines." (PMID 36591465, 2022). "Most importantly, the ensuing elevated angiogenesis directly elevated leptin levels in the tumour microenvironment." (PMID 36450983, 2022). "In this study, we found that leptin was highly expressed in the sera and tumor tissues of patients with NPC, and elevated leptin expression was associated with advanced clinical features and poor prognosis." (PMID 35778755, 2022). "For example, adipocytes from obese patients with breast cancer produce high levels of fatty acids and adipokines (such as leptin) to promote tumor progression." (PMID 35062950, 2022). "In an analysis of patient tumor samples, overall survival was significantly decreased in the leptin-high expression group compared with the low expression group." (PMID 36230617, 2022). "This study aims to identify a connection between excess adipose tissue assessed by calculating BMI and measuring waist circumference, serum level of adipokine leptin, and tumor immunohistochemical (IHC) characteristics." (PMID 35989732, 2022). "This phenomenon has been shown across multiple species, tissues and tumour models and is driven in part by leptin signalling." (PMID 36038791, 2022). "In line with previous studies, here, we demonstrated that leptin silencing by leptin targeting shRNA led to tumor growth attenuation in NPC cells." (PMID 35628510, 2022). "Leptin levels at tumour endpoint displayed a similar trend to pre-tumour endpoint levels, with a significant increase in leptin with HFD compared to CR and NCD." (PMID 35908046, 2022). "It has been observed that tumor formations can be suppressed by the increase in miR-506 and miR-150 expressions in leptin− and leptin+ cells, and they create a synergistic response in inhibiting cell proliferation with palbociclib." (PMID 37529006, 2022). "Recently, it was shown that the modulation of tumor cell growth by leptin is related to the genesis and development of various tumors, among which PC is a current clinical hotspot given its poor prognosis and difficulty in diagnosis." (PMID 35875143, 2022). "The complex and controversial role of leptin and adiponectin in supporting tumor growth needs further investigation to develop innovative therapeutic strategies." (PMID 35625629, 2022). "Consistent with cytokine array data and ELISA results, we also detected a reduction in leptin staining in the GLSECKO tumors compared with WT tumors by IHC on tumor sections." (PMID 36381236, 2022). "Adiponectin demonstrates the opposite effects with respect to leptin, meaning it shows anti-tumour activities including antiproliferative, antimigratory and proapoptotic." (PMID 36556428, 2022). "As shown in representative IHC images, leptin was primarily located in the cytoplasm in both adjacent non-tumor tissues and NPC tissues." (PMID 35778755, 2022). "With regards to NPC, only a limited number of studies were conducted to determine if leptin directly plays a role in modulating tumor progression in NPC." (PMID 35778755, 2022). "Our unpublished data showed that knockdown of endogenous leptin led to tumor growth inhibition in a xenograft model (manuscript under review)." (PMID 35628510, 2022). "This implies that leptin is able to promote tumour cell proliferation and adhesion by increasing E-cadherin expression." (PMID 36556428, 2022). "Consistently, abundant T memory cell populations are observed with concordant anti-tumor response in the TME after leptin-expressing oncolytic virus therapy." (PMID 35062950, 2022). "It has been shown that tumor formations are cell-dependent in Panc-1 and MiaPaCa-2 xenograft models after leptin applications." (PMID 37529006, 2022).
tumor (continued). "As judged by tumour lysate ELISAs, leptin levels were greater than 5× higher in total tumour tissue of SCC relative to papilloma." (PMID 36450983, 2022). "Serum leptin levels were found to be significantly higher in postmenopausal estrogen receptor-positive breast cancer patients with advanced tumor stage and distant metastases." (PMID 36361728, 2022). "Nevertheless, leptin was also reported to promote immune tolerance on several cell types and immune escape mechanisms in certain types of tumours." (PMID 35326405, 2022). "For example, engineering vaccinia viruses is able to increase the generation of adipokine leptin by tumor cells after viral infection, leading to the TME remodeling and enhanced anti-tumor response." (PMID 36618408, 2022). "Abundant studies have found that adipocytokines play important roles in tumor invasion and metastasis, among which resistin and leptin have been shown to promote metastasis in a variety of tumor models." (PMID 36361525, 2022). "As leptin is secreted by adipocytes within the breast tissue, leptin can alter the tumor microenvironment." (PMID 35186923, 2022). "Correspondingly, we observed indicated trend for leptin, sTie-2 and IL-8 progression through early EC stages, which illuminates how growing tumor mass dictates a higher need for additional oxygen and nutrient supply and accelerates angiogenic activity." (PMID 36505829, 2022). "Leptin plays an anti-tumor role by promoting the proliferation and activation of natural killer cells." (PMID 35463353, 2022). "Further validation of Lep in whole tumor lysate by ELISA with additional independent tumor samples showed that the levels of leptin were significantly decreased in tumors derived from GLSECKO mice relative to WT mice." (PMID 36381236, 2022). "Fat cells secrete inflammatory growth factors and cytokines; among these, leptin and interleukin 6 (IL-6) play roles in the activation of the mTOR signaling pathway and are involved in tumor progression and resistance to chemotherapy treatments." (PMID 35805003, 2022). "The application of adeno-associated virus-sustained leptin secretion causes a rapid weight loss of obese ob/ob-mice, which was associated with a reduction in PDAC tumor size." (PMID 36231132, 2022). "Leptin often plays a tumor-promoting effect through the STAT3 signaling pathway and stimulates cell proliferation, migration and invasion." (PMID 34485124, 2021). "Adipose tissue is associated with a chronic inflammatory state and secretes cytokines, such as adiponectin or leptin, with a direct impact on the tumor microenvironment." (PMID 34063692, 2021). "Adipocytes maintain crosstalk with cancer cells, fueling the tumor microenvironment with free fatty acids, leptin, ketone bodies, and other macromolecules that alter the metabolism in neoplastic cells." (PMID 34283044, 2021). "The pro-tumor role of leptin is usually due to its role in the promotion of angiogenesis and in enhancing the proliferation and survival of tumor cells." (PMID 34690923, 2021). "Immunohistochemical analysis of tumor samples from control, leptin, adiponectin or leptin + adiponectin treated mice showed similar findings." (PMID 34389732, 2021). "In the past, studies focusing on the communication between adipocytes and tumor cells were limited to soluble mediators such as leptin or proinflammatory cytokines." (PMID 34283044, 2021). "On the other hand, the linear regression model identified a significant correlation between higher relative serum levels of leptin on day seven and the distal tumour location, early N stage, Lauren diffuse type, and higher tumour grade." (PMID 34827598, 2021). "Taking for example adiponectin and leptin clearly reveals the ambiguous effect of AT secretes on tumor progression." (PMID 33916703, 2021). "Leptin has also been proposed to regulate autophagy, a process closely related to tumor progression." (PMID 33763424, 2021).
tumor (continued). "In murine models, high fat diet (HFD) increased the accumulation of myeloid-derived suppressor cells (MDSCs) via leptin and enhanced the immunosuppressive activity of tumor-infiltrating MDSC; MDSCs enhanced cancer progression by preventing T-cell activation." (PMID 34139486, 2021). "More rapid tumor progression was observed in leptin-treated group compared to control-group while tamoxifen treatment regressed tumors effectively." (PMID 34389732, 2021). "detected the antioxidant responses in three human mammary epithelial cells and confirmed that different regulatory effects of leptin on oxidative status depend on the tumor status of different mammary epithelial cells." (PMID 34350120, 2021). "On the other hand, there was a conflicting study showing that serum leptin level was positively correlated with BMI and inversely related to tumor stage and grade." (PMID 33639880, 2021). "Leptin changes closely reflected changes in IL-6, according to tumor objective response or progression." (PMID 33809200, 2021). "Crosstalk between Leptin and Notch signaling regulated the expression of miR343-3p, which inhibited tumor suppressor, KLF6 thereby affecting the chemosensitivity." (PMID 33968932, 2021). "In another preclinical study, obesity promoted PD-1-mediated T-cell dysfunction—partly via leptin signaling—and tumor growth." (PMID 34139486, 2021). "Leptin induced oncogenic miRs (miR-21, miR-96, miR-31, miR-182) and reduced tumor suppressor miRs (miR-143, miR-26b, miR-27b, MiR-489)." (PMID 33482868, 2021). "First discovered for its role in suppressing appetite and regulating energy expenditure, in vitro and in vivo studies have shown that beyond the metabolic functions, leptin is able to promote cell proliferation and migration and tumor growth." (PMID 33587254, 2021). "A similar role has been reported in colon cancer, where leptin acts as a growth factor at stages correlating with tumor initiation in a murine model." (PMID 33987528, 2021). "The inhibitory effects of globular adiponectin on leptin-promoted inflammasome activation and tumor growth were further verified in breast MCF-7 cell and xenograft models via mechanisms including HO-1 induction and ER-α signaling modulation." (PMID 33799880, 2021). "Leptin further appeared to serve as an independent predictor for high hazard ratios compared with the patient’s tumor (T), node (N), and metastasis (M) (TNM) status and clinical stage (p = 0.006, multivariate)." (PMID 33804101, 2021). "Briefly, our results suggest a strong suppression of CYP19 expression in the tumor tissue during treatment with exemestane even in women with elevated leptin levels." (PMID 34554372, 2021). "In vitro experiments have also confirmed that lower adiponectin levels in obese people are a prerequisite for leptin to promote tumor growth and promote tumor progression." (PMID 34485124, 2021). "Overproduction of hormones (e.g. oestrogen), adipokines (e.g. leptin), and insulin that promote tumour cell survival and proliferation leads to tumour growth." (PMID 34302062, 2021). "Cytokines released from adipose tissue such as adipokines, leptin, and resistin, among others, are also believed to facilitate tumor progression." (PMID 34212054, 2021). "MMP2 and MMP9 production by tumor cells were described to also be controlled by adipocyte-derived leptin and IL-6 through the activation of the FAK- and Src-dependent pathways." (PMID 33917351, 2021). "Together with cells from the innate and adaptive immune systems and cytokines (e.g., tumor necrosis factor alpha [TNFα] and interleukin [IL]-6), leptin can generate a pro-inflammatory stage in the tumor microenvironment." (PMID 34868066, 2021). "The expressions of metastatic and EMT genes (SERPINE1, IL-6, and MMP-2) were induced in tumor cells by MSCs secreted leptin." (PMID 33472580, 2021).